ACE (angiotensin I converting enzyme)
Diseases named in the same sentence as ACE in open-access papers (continued):
Sharing a sentence is not in itself a finding about the gene and the disease.
diabetes (continued). "Therefore, this study aimed to investigate hemodynamic and autonomic control as well as the renal expression level of Ang II after induction of diabetes in genetically modified mice harboring a different number of copies of the ACE gene." (PMID 30088535, 2018). "Accordingly, nutritional composition, the content of phytochemical antioxidants and the inhibitory ability of key enzymes with impacts on obesity and diabetes (α-glucosidase and pancreatic lipase) or on arterial pressure (angiotensin-I converting enzyme) were assessed." (PMID 30274353, 2018). "Accordingly, nutritional composition, the content of phytochemical antioxidants, and the inhibitory ability of key enzymes with impacts on obesity and diabetes (α-glucosidase and pancreatic lipase) or on arterial pressure (angiotensin-I converting enzyme), were evaluated." (PMID 30274353, 2018). "Additionally, a small retrospective analysis of patients on ACE inhibitors reported the incidence of hyperkalemia to be higher in those with chronic renal failure and diabetes." (PMID 29558445, 2018). "Interestingly, we also observed that diabetes up-regulates ACE mainly in serum, lung, heart, and liver, and ACE2 mainly in serum, liver, and pancreas." (PMID 28273875, 2017). "The association remained significant when fasting insulin, eGFR, smoking, diabetes, ACE inhibitors, sartans or diuretics treatments, use of metformin and pioglitazone were added to the model, but its independence was not retained after inclusion of fibrinogen and ESR values into the model." (PMID 28415730, 2017). "Prescription of ACE inhibitors and ARBs in AI/AN with diabetes increased 76% from 1997 to 2002." (PMID 28081061, 2017). "It should be noted that, despite propensity score matching, thepatients in the statin group had CAD, diabetes, peripheral vascular disease,aspirin use, and ACE inhibitors/angiotensin receptor blockers morefrequently than the patients in the group without statins." (PMID 29044300, 2017). "The angiotensin-converting enzyme (ACE) gene, plays an critical role in modulating vascular tone through hydrolyzing angiotensin I to vasoconstrictory peptide angiotensin II, which seems to be particularly biologically and clinically relevant to diabetes." (PMID 27854313, 2016). "When comparing metformin users to those without diabetes, metformin use was significantly associated with being black, increased BMI, decreased alcohol use, decreased antacid use, and increased ACE inhibitor use." (PMID 27513580, 2016). "This might partly explain the reduced risk of developing diabetes and metabolic syndrome with RAS antagonists and offer insight into the origins of cardiovascular disease in which UCPs and ACE both play a role." (PMID 27347560, 2016). "Raw garlic aqueous extract (GE) has ameliorative actions on the renin-angiotensin system in type-1 diabetes mellitus (DM); however its effects on plasma and kidney angiotensin I converting enzyme type-1 (ACE-1) and angiotensin II (AngII) require further elucidation." (PMID 27293465, 2016). "A number of studies have reported that patients suffering from DR have high circulating levels of ACE, which implies that elevated serum ACE levels might be a possible hazard factor in destroying retinal vascular apparatus in subjects suffering from diabetes." (PMID 27854313, 2016). "In assessment of association between CAD and diabetes in Iranian population the following genes showed significant association: paraoxonase 1, adiponectin, eNOS, CETP, AT1R, resistin, MMP-3, BChE K, Apo E, ACE." (PMID 26587547, 2015). "Recent studies indicate that commonly used drugs in diabetes, including ACE inhibitors, DPP4 inhibitors, GLP-1 agonists, insulin, metformin, statins, or thiazolidinediones, may increase the number of EPCs and improve EPC function." (PMID 26077117, 2015).
diabetes (continued). "ACE inhibition was shown to reduce the accumulation of serum AGEs in diabetes, possibly via effects on oxidative pathways and by increasing the production and secretion of sRAGE into plasma as shown with perindopril which caused an increase in plasma sRAGE in patients." (PMID 26491434, 2015). "However it is possible that, despite restoring a normal PIV, ACE inhibitors fail to restore the diabetes skin ability to resist to ischemia, if this later effect depends upon non-AT1 receptors activation." (PMID 25888905, 2015). "Aguilar and Solomon suggested that ACE inhibitors may prevent the onset of diabetes and Andraws and Brown could confirm this effect in a meta-analysis." (PMID 24816436, 2014). "Analysis of the clinical course of the three ACE genotypes revealed that the majority (95%) of patients with the DD genotype who had albuminuria progressed to end-stage renal disease within 10 years of diagnosis of diabetes." (PMID 25587546, 2014). "Moreover, angiotensin converting enzyme (ACE) inhibitors or AT1 antagonists attenuate carotid atherosclerosis during diabetes by improving vascular function." (PMID 24877125, 2014). "The associations of 23 SNPs located within 17 candidate genes (MTHFR, PPARγ, LPL, INSIG, TCF7L2, FTO, KCNJ11, JAZF1, CDKN2A/B, ADIPOQ, WFS1, CDKAL1, IGF2BP2, KCNQ1, MTNR1B, IRS1, ACE) with overweight and obesity, diabetes, metabolic phenotypes, and MetS were examined in both studies." (PMID 24959828, 2014). "Landmark trials such as Action in Diabetes and Vascular Disease: Preterax and Diamicron MR Controlled Evaluation (ADVANCE), Action to Control Cardiovascular Risk in Diabetes study, ONTARGET® and TRANSCEND® have shown CV and renal benefits with ACE inhibitors or ARBs in patients with T2DM." (PMID 23866091, 2013). "After adjusting for confounding variables, diabetes was significantly associated with urinary ACE2 activity (p = 0.003) and protein levels (p<0.001), while female gender was associated with urinary mRNA levels for both ACE2 and ACE." (PMID 22629438, 2012). "Conversely, ACE2 deletion disrupted the benefits of ACE inhibition on diabetic nephropathy in streptozotocin-induced diabetes suggesting that ACE inhibition may enhance ACE2 activity." (PMID 22121476, 2012). "Because there is no large scale study on the effectiveness of blocking the RAS for the prevention of diabetes in "real world" clinical practice we designed the ACE inhibitor-based versus diuretic-based antihypertensive primary treatment in patients with prediabetes (ADaPT) study." (PMID 22230104, 2012). "For patients with diabetes mellitus, a Swedish study including 229 primary care centres revealed - similar to our study - that men were more often prescribed ACE inhibitors than women and that only one third of the patients below 75 years was on lipid-lowering drug therapy." (PMID 22838970, 2012). "However, patients with diabetes were more likely to be treated with glycoprotein (GP) IIb/IIIa antagonists, angiotensin-converting enzyme (ACE) inhibitors, or beta-blockers (BBs)." (PMID 22778703, 2012). "Higher percentages of patients in diabetes with microalbuminuria group were on ACE inhibitors." (PMID 21748022, 2011). "ACE inhibitors might protect the basement membrane of the ciliary body in a similar manner and protect against diabetes-related changes in aqueous production." (PMID 20573241, 2010). "Cox regression analysis showed that diabetes mellitus (HR 2.36, 95% CI 1.33-4.46, p = 0.003), 4G/4G polymorphism of PAI-1 gene (HR 3.45, 95% CI 1.71-6.56, p = 0.009), and D/D polymorphism of ACE gene (HR 2.99, 95% CI 1.84-5.76, p = 0.005), were independent predictors of the MACE." (PMID 28352370, 2010). "In the first meta-analysis of 13 trials that included 93,451 patients without diabetes at baseline, randomisation to ACE inhibitor- or ARB-based therapy was associated with a 26% reduction in risk of developing diabetes (p < 0.001)." (PMID 19220522, 2009).
diabetes (continued). "Ramipril is an ACE inhibitor (ACEi), that has been shown to reduce cardiovascular events in high risk patients and post-hoc analyses of the HOPE trial have provided evidence for its beneficial action in the prevention of diabetes." (PMID 18652658, 2008). "In a recent meta-analysis Elliott and colleagues showed that increased blood sugar values and the subsequent development of diabetes occur more often in patients receiving diuretics and betablockers instead of angiotensin receptor blockers (ARBs) and angiotensin converting enzyme (ACE) inhibitors." (PMID 19000308, 2008). "However, among patients with IHD and diabetes, only 11% of patients were prescribed the combination of antiplatelet agent, ACE-inhibitor, and statin medications." (PMID 17173679, 2006). "In this study, we investigated the ACE gene I/D polymorphism in TCP patients (without diabetes mellitus), FCPD patients and healthy controls to understand its association with the disease." (PMID 17163998, 2006). "However, ACE levels should be interpreted cautiously, as they may also be elevated in other systemic conditions such as diabetes mellitus, hyperthyroidism, and liver disease." (PMID 40741038, 2025). "Moreover, genetic variations in insertion/deletion (I/D) polymorphisms at angiotensin-converting enzyme gene (ACE) and T/C polymorphisms in the angiotensin type 1 receptor gene (AGTR1) are related to diabetes and lipid levels, but the associations are controversial." (PMID 39080710, 2024). "Furthermore, in elderly Chinese females, TG and TG/HDL-C levels might be more susceptible to the cumulative effect of ACE I/D and AGTR1 rs5182 as well as their combined effect with diabetes." (PMID 39080710, 2024). "Similarly, hypertensive patients with diabetes or chronic kidney disease may prefer ACE inhibitors or ARBs due to their additional renal protective effects." (PMID 39289597, 2024). "Finally, the Ongoing Telmisartan Alone and in combination with Ramipril Global Endpoint Trial (ONTARGET) and the Veterans Affairs nephropathy in Diabetes (VA Nephron D) study showed that the combination of ACE inhibition and ARB together lead to more adverse events with little additional benefit." (PMID 38105902, 2023). "Angiotensin-Converting-Enzym(ACE)-Hemmer und Angiotensin-Rezeptor-Blocker (ARB) gehören zu den Medikamenten der ersten Wahl für die Behandlung von Patient:innen mit nichtdialysepflichtiger CKD mit häufigen Komorbiditäten wie Hypertonie und Albuminurie oder Diabetes mellitus und Albuminurie." (PMID 37193862, 2023). "Moreover, ACE-inhibitors were rarely used, despite their established benefits in diabetes." (PMID 34327415, 2021). "However, captopril exerted significantly higher protective effects against renal complications of diabetes than curcumin did, which could be attributed to the more potent ACE inhibitory effects of captopril than curcumin." (PMID 33925121, 2021). "Therefore, it is expected that the use of RAS inhibitors including ACE inhibitors and angiotensin II receptor blockers may inhibit diabetes-induced pyruvate and fumarate upregulation." (PMID 33255934, 2020). "Traditional treatments for diabetes related cardiovascular complications include the combination of dietary modification as well as a cocktail of pharmacological agents that can include insulin sensitizers, beta blockers, angiotensin converting enzyme (ACE) blockers and statins." (PMID 30669379, 2019). "Moreover, they speculated that reduced ACE2 expression and upregulated ACE expression gradually induce kidney damage in diabetes." (PMID 29582239, 2018). "Thus, the differences we observed may be explained in part by the more prevalent ACE inhibitor use, but less frequent use of diuretics in individuals with diabetes." (PMID 30364090, 2018). "In patients who have vascular disease or high-risk diabetes without heart failure, ACE inhibitors reduce mortality and morbidity from cardiovascular causes, but the role of ARBs in such patients is unknown." (PMID 28725272, 2017).
diabetes (continued). "However, diabetes was not implicated in the change of plasmatic ET-1 and ACE activity and complications of metabolic syndrome due to the used of drug and the recommended diet." (PMID 27894250, 2016). "However, a causal link between higher levels of ACE, angiotensin peptides, and kidney malfunction in association with diabetes has not been completely established." (PMID 26442284, 2015). "Traditionally, ACE inhibitors (ACEIs) and angiotensin II type 1 receptor blockers (ARBs) have been widely used in everyday clinical practice of nephrology for the purpose of reducing proteinuria in patients with various renal diseases including diabetes mellitus." (PMID 25587546, 2014). "The VALIDATE-D study is the first human intervention study to evaluate whether direct VDR activation can lower the human RAS in diabetes, compared to the effect of an ACE inhibitor, and whether this mechanism can translate to clinically relevant endpoints for diabetic kidney disease." (PMID 23971740, 2013). "In addition, age of diagnosis, systolic blood pressure, diastolic blood pressure and diabetes mellitus were also identified as ACS risk factors in univariate analyses, though only the ACE DD genotype and age of diagnosis were found to be independent risk factors." (PMID 22333273, 2012). "The prevalence of cardiovascular disease and diabetes appears to be higher in this cohort compared to an earlier study in the Midlands with a predominantly White British population, however the proportion of patients prescribed medications such as ACE-inhibitors and beta-blockers has also increased." (PMID 22533538, 2012). "Hence, the aqueous flow effect was more likely due to the diabetes than the ACE inhibitor." (PMID 20573241, 2010). "For example, β-blockers, diuretics, and angiotensin converting enzyme inhibitors (ACE inhibitors) can interact with diabetes medications and mask the adrenergic symptoms of hypoglycemia, complicating diabetes management." (PMID 41303475, 2025). "SCFAs: Short-chain fatty acids; TMAO: Trimethylamine-N-oxide; LPS: Lipopolysaccharide; NO: Nitric oxide; ACE: Angiotensin-converting enzyme; IR: Insulin resistance; T2DM: Type 2 diabetes mellitus." (PMID 40535952, 2025). "(Diabetes-specific) Medications included, among others, GLP-1 receptor agonist (Dulaglutide, n = 1) Metformin (n = 7), Statins (n = 5), ACE inhibitors (n = 3), Basal insulins (n = 3)." (PMID 40962878, 2025). "The expressions of IL17A, ACE, TLR4, and IL6 are up-regulated with diabetes that promote the progression of gangrene, whereas the expressions of FGF2 and IGF1 are down-regulated." (PMID 40657379, 2025). "The ACE I/D genotype (Model A) or AGTR1 rs5182 genotype (Model B) was used as an independent variable separately or in combination with age, gender, diabetes mellitus, and the use of antidiabetic drugs or lipid-lowering drugs as other independent variables." (PMID 39080710, 2024). "The use of medications like ACE inhibitors or angiotensin receptor blockers (ARBs) to manage microalbuminuria could help reduce both renal and cardiovascular risks, aligning with evidence that controlling renal dysfunction improves cardiovascular outcomes in diabetes." (PMID 39583612, 2024). "The findings of the present study suggest potential interactions among gender, ACE I/D, AGTR1 rs5182 and diabetes mellitus in terms of lipid and lipid ratios, especially in terms of TG levels and the TG/HDL-C ratio." (PMID 39080710, 2024). "Such an understanding may suggest the development of personalized treatments based on ACE and AGTR1 genetic polymorphisms to lower elevated TG levels in elderly diabetic female patients that have the potential to normalize the dyslipidaemia induced by diabetes mellitus." (PMID 39080710, 2024). "In our study, baseline blood pressure values were comparable across classes, but beta-blockers, ACE inhibitors, and ARBs were more often prescribed among specific groups, including those with a history of CVD or diabetes." (PMID 36394298, 2023).
diabetes (continued). "Another study on male C57BL/6 mice with STZ-induced diabetes showed that cur-cumin analog, C66, efficiently attenuated diabetic renal injury via inhibition of MAPK-mediated ACE expression and RAS activation." (PMID 37047589, 2023). "It has been shown that rather than the actual stroke itself, the key factors related to post-stroke impaired sexual activity were angiotensin-converting enzyme (ACE) inhibitors, diabetes mellitus, and depression." (PMID 37373681, 2023). "Several studies have demonstrated an over-activation of the RAS in diabetes problems, and the RAS pathway involves ACE." (PMID 37342546, 2023). "Most of the patients were treated with ACE inhibitors/ARB and beta-blockers, and 40% had a history of diabetes." (PMID 36277746, 2022). "In conclusion, our results illustrated an independent connection between ACE serum levels and smokers with CHD and diabetes." (PMID 36110446, 2022). "Others, such as obesity, diabetes mellitus and family history of CVD at a young age, stimulate ACE synthesis, which leads to an excessive vasoconstriction, enhancing the ischemic risk." (PMID 34834033, 2021). "In this regard many drugs can modulate this ratio with therapeutic implications for patients with obesity and diabetes: insulin reduces ACE2 expression, but GLP-1 agonists, pioglitazone, ACE inhibitors, and statins upregulate ACE2, reducing the ACE/ACE2 ratio." (PMID 33648564, 2021). "We found that diabetes significantly increases the expressions of angiotensin II receptor type 1 (AT1) and angiotensin II generating enzyme (ACE) in the kidney, which are restored by DL-NBP treatment." (PMID 34497508, 2021). "The US Renal Data System reports that only 26% of patients with CKD received medical evaluation with serum creatinine level, lipid levels, and microalbuminuria in 2007, and only 67% of individuals with diabetes and CKD received ACE inhibitors/ARBs." (PMID 34401719, 2021). "Nevertheless, the administration of ACE and ARB inhibitors to treat diabetes in COVID-19 patients is controversial." (PMID 34205044, 2021). "The precise nature of the dysregulation, however, is much less clear, with claims and counter-claims as to the relative expression of ACE and ACE2 in diabetes; certainly evidence from animal models appears to point to down-regulation of ACE2 in the kidney." (PMID 33614744, 2020). "Lycopene reduces angiotensin converting enzyme (ACE) activity, the level of which can indicate diabetes or complications related to diabetes." (PMID 33375293, 2020). "Current therapeutic strategies such as angiotensin converting enzyme (ACE) inhibitors and angiotensin-I receptor blockers (ARBs) target the RAAS and provide a degree of renoprotection in diabetes." (PMID 33396868, 2020). "Until now, various bioactivities of these peptides, such as antioxidative, anti-cancer, angiotensin-I converting enzyme (ACE) inhibitory, anti-diabetes, and anti-microbial, have been explored." (PMID 33233577, 2020). "It is frequent among hospitalized patients as it is related to type 2 diabetes mellitus (T2DM) and common medications such as ACE-inhibitors (ACE-is) and trimethoprim-sulfamethoxazole (TMP-SMX)." (PMID 33133704, 2020). "For the treatment of hypertensive patients with diabetes and albuminuria, an angiotensin II receptor blocker (ARB) or an angiotensin converting enzyme (ACE) inhibitor is recommended as a first-line treatment." (PMID 31239535, 2019). "In a human study, perindopril, an angiotensin-converting enzyme (ACE) inhibitor, reduced plasma ADMA levels in 11 non-insulin-dependent diabetes mellitus patients." (PMID 31357472, 2019). "The other works report the biological activities merely against angiotensin converting enzyme (ACE), digestive enzymes related to diabetes, and the antioxidant and anti-inflammatory as well as cytotoxic activity of essential oils." (PMID 32116669, 2019).